BRCA2 (BRCA2 DNA repair associated)
Diseases named in the same sentence as BRCA2 in open-access papers (continued):
Sharing a sentence is not in itself a finding about the gene and the disease.
tumor (continued). "In addition, in one patient, we found an abnormal junction from the BRCA2 exon 20 to exon 25 in the tumor breast tissue sample that was not present in the corresponding normal tissue." (PMID 37046838, 2023). "The somatic NAHR burden did not vary by tumor type nor was it lower in tumors harboring biallelic pathogenic mutations in DNA repair genes, including frequently mutated homologous recombination pathway mediators (BRCA1, BRCA2, PALB2 and RAD51C)." (PMID 37945902, 2023). "Alternatively, changes in pathways that compensate for the loss of Polθ activity could conceivably cause resistance, as could molecular changes that compensate for dysfunction in the tumour suppressor being synthetic lethal targeted by a Polθi (e.g. BRCA1, BRCA2)." (PMID 35567571, 2022). "However, in the recent cohort an atypical tumour phenotype was present in 15.8% (12/76) of non-BRCA1/BRCA2 MINAS cases (though not all studies presented individual patient-level data)." (PMID 34983940, 2022). "While the two remaining hyper-deleted tumours, BRA08 (European) and KAL0013 (African), showed no BRCA2 loss, two or more nonsynonymous germline BRCA2 mutations were observed for each patient, although defined by ClinVar [December 2020] as ‘benign’ or of ‘uncertain significance’." (PMID 36045381, 2022). "However, the specific functions of BRCA2 required for tumor suppression have not been rigorously identified." (PMID 36098506, 2022). "We also include an analysis of the genomic and transcriptomic landscape of the DDR PARP genes and key HR genes (BRCA1, BRCA2, ATM, RAD51, MRE11, PALB2) in GI patient tumours (n = 1744) using publicly available datasets to identify patients that may benefit from PARPi therapeutic approaches." (PMID 34440228, 2021). "The pooled odds ratio analysis showed a significant relationship between higher PARP expression and larger tumour size, poor tumour differentiation, lymph node metastasis, distant metastasis, higher TNM stage and lymphovascular invasion, and positive immunoreactivity for Ki-67, BRCA1, and BRCA2." (PMID 34830749, 2021). "In the tumor of the LUSC donor TCGA-66-2744, the allele harboring the pathogenic germline BRCA2 mutation was lost due to LOH, thus the wild-type allele was retained, and consequently, it is probably not a BRCA2 deficient case." (PMID 34145376, 2021). "It is conceivable that the reduced replication speed caused by p21 upregulation could confer a survival advantage to cells and tumours lacking BRCA2." (PMID 34389725, 2021). "No carriers of the tumour BRCA1 and/or BRCA2 mutations were identified in the patient group." (PMID 34444865, 2021). "Importantly, at concentrations that elicited cell inhibition in BRCA1 or BRCA2 mutant cells, ART558 had minimal effects in non-tumour epithelial cells such as the human mammary epithelial cell lines, MCF10A, MCF12A and HMLE3, or in BRCA-gene wild type CAL51 triple-negative breast tumour cells." (PMID 34140467, 2021). "However, as expected, the germline BRCA2 c.156_157insAlu variant was not called by the NGS tumor assay pipeline, using the software Sophia DDM®, in two tumor samples from the validation series." (PMID 32850417, 2020). "No carriers of tumor BRCA1 and or BRCA2 mutation were identified in the patient group." (PMID 33374116, 2020). "Furthermore, PEG3 mutation was significantly associated with high TMB and inferior prognosis, and the associations were independent of multiple confounding factors including age, tumor stage and mutations of BRCA1, BRCA2 and POLE." (PMID 32729618, 2020).
tumor (continued). "Although promoter methylation of BRCA1 and of BRCA2 gene has not been widely assessed in ovarian cancers, this mechanism is well known to affect other tumor suppressor genes, and, importantly, it is easy to detect in routine diagnostics even when FFPE tumor tissue is the only available material." (PMID 33352687, 2020). "Therefore, the specific tumor location in the head of the pancreas in Palb2-KPC and Brca2Δex3-KPC mice might be due to ablation of PALB2-BRCA2 interaction." (PMID 31877165, 2019). "However, this is not unique to the T-cell lineage, as BRCA2 can function as a haploinsufficient tumor suppressor during pancreatic transformation." (PMID 31721781, 2019). "Enrichment for negative prognostic factors in BRCA2-mutant PCa harbouring IDC suggested that these tumours may have distinct evolutionary trajectories." (PMID 28067867, 2017). "Supportive of this postulate is a similar rate of an absence of locus-specific LOH in BRCA2 carriers in the two independent tumor sets, similar HRD-Mean scores to nonBRCA tumors and higher percentage of aging signature in those tumors without BRCA locus-specific LOH in the Penn data set." (PMID 28831036, 2017). "No significant relation was observed between the tumor grade, and expression of Rad51 or BRCA2." (PMID 25909291, 2015). "Interestingly, preclinical and clinical trials have been successful not only in tumours with deficiencies in the double-stranded DNA repair, such as mutations in BRCA1 and BRCA2, but also in tumours that have no defects in the HRR." (PMID 26339143, 2015). "Also in the studies included in this review, there were many differences reported in tumour characteristics between BRCA1 and also BRCA2 mutation carriers compared to ‘non-carriers’ (part A)." (PMID 25816289, 2015). "Whether or not these roles for BRCA2 may explain the effect of heterozygosity in tumour development is yet to be explored." (PMID 24268522, 2014). "Given that Capan-1 is a BRCA2 deficient model, we investigated the possibility that medium depth, whole genome sequencing could be used to distinguish BRCA1 and BRCA2 deficient tumours from non-familial forms." (PMID 21750719, 2011).
tumor (continued). "Similarly, the presence of an ER-positive tumour in the family may result in combined BRCA1 and BRCA2 carrier probabilities <20%." (PMID 20482762, 2010). "Interestingly, we observed two familial-BRCA2 tumours without deletion or allelic imbalance at the BRCA2 locus and these tumours did not display large-scale genomic instability." (PMID 19589159, 2009). "In addition, we found high-level amplifications at 1q43–q44 and deletions at chromosome 14q, which have not been described before in relation with familial BRCA2 tumour development." (PMID 19589159, 2009). "However, two familial BRCA2 tumours were found within this cluster, neither of which displayed deletion or allelic imbalance at the BRCA2 locus and both had an extremely low GII, that is less than 0.034, and were of basal-like phenotype." (PMID 19589159, 2009). "There is little evidence that BRCA2 plays a gatekeeper role for neoplasia." (PMID 16417627, 2006). "Among the BRCA2 families, the opposite was found, with a significantly higher frequency of tumours negative for oestrogen and progesterone receptors among the older patients than among the other groups, but no distinctive tumour characteristics among the younger BRCA2 patients." (PMID 15987451, 2005). "Given that cell line collections are not representative of BRCA1‐ and BRCA2‐altered patient tumour response to PARP inhibitors, we hypothesised that an isogenic model hosting specific gene alterations would be more appropriate to explore cellular responses to PARP inhibitor treatment." (PMID 40977519, 2025). "Notably, several mutations (5× BRCA2, 4× ERBB2, 2× NRAS, 2× HCN1 [hyperpolarization-activated cyclic nucleotide-gated potassium channel 1]) were detected more than once in plasma or stool samples across all patients but never in tumor biopsies." (PMID 38766867, 2024). "Hence, it is hypothesised that while the adjacent normal cells in the stage II and stage III HNSCC patients had elevated APE1 expression, they also upregulated BRCA2 and XPD expression under the influence of the tumour cells in an effort to suppress their own carcinogenic transformation." (PMID 37113717, 2023). "Notably, BRCA2 overexpression failed to fully restore HCC tumor cell growth following USP21 depletion, suggesting that USP21 may have other targets in HCC." (PMID 35846989, 2022). "Furthermore, the high prevalence of genes such as MLL, MLL2, and BRCA2 suggest that other chromatin remodeling motifs may be involved in tumorigenesis of these patients rather than an event specific to a particular tumor type." (PMID 32045431, 2020). "Interestingly, BRCA1, BRCA2 andPALB2 heterozygous mice could not be distinguished from wild-type animals,corroborating the classic recessive model for tumor suppression, at least in animalmodels." (PMID 31067289, 2019). "In our BRCA2 –mutated xenograft, we did not observe an increased phosphorylation of ERK nor a decreased in BRCA1 gene expression after mTOR inhibition, indicating that this mechanism is not involved in the anti-tumor effect of olaparib and everolimus combination." (PMID 30038706, 2018). "Importantly, we provide evidence that a defect in USP21-mediated BRCA2 stabilization impairs the growth of BRCA2-proficient HCC tumor cells, and consistent with this, USP21 levels inversely correlate with HCC patient survival, pointing to USP21 as a potential target for HCC tumor therapy." (PMID 28743957, 2017).
tumor (continued). "We present the results of integrated analysis of miR/mRNA data from the same tumor tissue samples to identify genes that could differentiate between tumor harvested from young patients (aged ≤35 years) with familial BC and those from sporadic BC, not harboring BRCA1/BRCA2 mutations." (PMID 25006670, 2014). "Therefore no support was found for the hypothesis of a predisposing tumour suppressor gene similar to the BRCA1 and BRCA2 genes." (PMID 20637093, 2010). "Similarly, Brca1 and Brca2 heterozygosity did not affect tumor formation induced by the Wnt-1 transgene, and partial deletion of the INK4a locus that encodes both p16INK4a and p19ARF did not result in increased DMBA-induced tumor formation." (PMID 19267898, 2009). "Second, our finding of 8.6% prevalence of occult tumours is established in BRCA1 mutation carriers undergoing prophylactic salpingo-oophorectomy, while other series did not make a clear distinction between a salpingo-oophorectomy or an oophorectomy, nor between BRCA1 and BRCA2 carriers." (PMID 15083174, 2004). "That fusion-positive case, which has been reported as SDC, harbored additional driver alterations (BRCA2 and PTEN) in addition to the FGFR3::TACC3 fusion; the morphology of the tumor has not been illustrated." (PMID 39387893, 2025). "Conversely, the stage of recurrent tumor, histological subtype, locoregional involvement of primary and recurrent tumors, and BRCA1 and BRCA2 status did not significantly affect HER2 conversion." (PMID 40282854, 2025). "The presence of rare subclones without BRCA2 homozygous deletion prior to treatment was confirmed by FISH and RNAish on tumor biopsies." (PMID 39577422, 2024). "miR-675 expression correlates with age, menopausal status, tumor size, histology, clinical stages, ER status, HER2 status, non-TNBC, BRCA1 status, and BRCA2 status (P<0.05), but not with other clinical pathological parameters." (PMID 39267845, 2024). "Unlike many other tumor suppressors, BRCA1/BRCA2 inactivation leads to embryonic lethality in mice and inhibits cellular proliferation in human and murine cells in vitro." (PMID 39198848, 2024). "However, the established role of FANCA, SLX4, BRCA2, and ATRX in DNA repair pathways is unlikely to be coincidental, especially considering that we identified mutations in other DNA repair pathway genes, including ATR, which was mutated in two tumours in our study." (PMID 39766052, 2024). "Tamoxifen has shown effectiveness in BRCA2 carriers, who often have estrogen receptor-positive tumours, unlike BRCA1 tumours, which typically present as triple-negative." (PMID 39421188, 2024). "The tumor stage (T) classification was predominantly T2 for BRCA1 carriers and noncarriers, while for BRCA2 carriers, T2 and T3 were more common (p = 0.260)." (PMID 37485802, 2023). "Importantly, tumours associated with germline PVs in BRCA1 (gBRCA1m) tend to have higher histologic grades and are more likely to yield triple-negative tumours (58.1%) compared to tumours associated with germline PVs in BRCA2 (gBRCA2m) and noncarriers (34.4% and 7.5%, respectively)." (PMID 38414963, 2023). "This is exemplified by PARPi used to treat breast, prostate, pancreatic or ovarian cancers with defects in the HR pathway, controlled by the tumour suppressors including (but not exclusive to) BRCA1, BRCA2, PALB2, RAD51C and RAD51D." (PMID 35567571, 2022). "In contrast, the combination of pyridostatin with NU‐7441 or paclitaxel showed an anti‐tumoral effect superior to each single drug against BRCA2−/− HCT116 tumours, although they did not prevent tumour growth in the long term." (PMID 35107878, 2022).
tumor (continued). "Tumor cell lines lacking functional BRCA1 and BRCA2 genes had increased sensitivity to platinum and DNA-damaging agents, such as anthracyclines." (PMID 36613648, 2022). "Around 11–18% of OC have germline BRCA1/BRCA2 PV and another 6–9% have a somatic BRCA1/BRCA2 PV in the tumour tissue alone which is not inherited." (PMID 34503154, 2021). "Assessment of individual tumor‐level data indicates that HR alterations are not mutually exclusive, and the most frequently altered HR gene is NBN (22%), while BRCA1 and BRCA2 are altered in ~ 7 and 8% of these tumors, respectively." (PMID 30467127, 2018). "Eight patients, who were BRCA1 and BRCA2 wild type carriers with luminal HER2 negative tumors, had their tumor and normal exomes sequenced." (PMID 29854292, 2018). "Thus, BRCA2 may not follow the classical Knudson “two hit” paradigm for tumour suppression." (PMID 24268522, 2014). "Due to early age of tumor onset, patient 1 was also tested for BRCA1/2 (data not shown) and a polymophic change was detected at BRCA2 exon 10 (N372H)." (PMID 19046423, 2008). "Moreover, tumor testing, at least for the BRCA1 and BRCA2 genes, is recommended for all women who test negative for germline pathogenic variants." (PMID 37241036, 2023). "No BRCA1 alterations were found in 22% of the tumor samples sequenced with the GeneReader, in 10% with the Ion S5TM and in 4% with the MiSeqTM, whereas no BRCA2 alterations were detected in 2% of the tumor samples sequenced with the GeneReader, but not with the Ion S5TM or the MiSeqTM." (PMID 35251494, 2022). "To determine whether the pyridostatin/NU‐7441/paclitaxel combination specifically suppresses growth of BRCA‐deficient, but not BRCA‐proficient tumours, we established xenograft tumours using BRCA2+/+ and BRCA2−/− HCT116 human cells." (PMID 35107878, 2022). "However, for assessing the occurrence of tumour types that are atypical for the relevant CSGs, for non-BRCA1/BRCA2 MINAS combinations, the number of instances of specific CSG combinations was generally very small." (PMID 34983940, 2022). "When BRCA1 and/or BRCA2 is defective, nonhomologous end-joining (NHEJ) with no requirement for homologous template is an alternative process used to repair DSBs with potential genome instability, which accelerates tumor development." (PMID 32980867, 2020). "Of the seven tumor samples without high frequent BRCA1/2 SNVs (P23-P25 and P30-P33) all but one case (P31) had heterozygous deletions of the complete BRCA1 and/or BRCA2 gene detected by CNV-calling." (PMID 31029168, 2019). "In addition, BRCA2 ASO treatment alone induced a minimal but significant reduction in cell proliferation (~20%) in both non-tumor HK-2 and A549 tumor cells, but no potentiation of olaparib-mediated inhibition of proliferation in HK-2 cells was observed." (PMID 26959114, 2016). "Thus tumor genomic profile evidences intact functioning of BRCA1 and BRCA2 and no homologous recombination defect." (PMID 26426992, 2015). "Tumor cells lacking BRCA1 and BRCA2 are sensitive to PARP inhibitors." (PMID 24784564, 2014). "Our results show that incorporating tumour marker information into BOADICEA may result in the better discrimination between BRCA1 carriers, BRCA2 carriers and nonmutation carriers." (PMID 20482762, 2010). "The characteristics of patients differed in the two groups, in that features linked to an aggressive course (premenopausal status, poorly differentiated tumours, ER negative, node positive) were or tended to be more frequent in BRCA (predominantly BRCA2) positive patients." (PMID 15996267, 2005).